DLL4 (delta like canonical Notch ligand 4)
Diseases named in the same sentence as DLL4 in open-access papers (continued):
Sharing a sentence is not in itself a finding about the gene and the disease.
tumor (continued). "The combined dysregulation of VEGF/VEGFR, BMP9/ALK1 and Dll4/Notch signaling pathways can lead to a more profound effects on tumor angiogenesis delaying the development of acquired resistance to VEGFR TKI in RCC." (PMID 27248821, 2016). "Adding chemotherapeutic agents to the Dll4 cocktail inhibited the induction of anti-apoptotic genes and resulted in further additive anti-tumor activity by decreasing the CSC population." (PMID 26713603, 2016). "Our findings suggest that miR-27b has different effects on tumor cells and the cells of tumor microenvironment as is evidenced by its disparate effect on Dll4 expression in the tumor and tumor vasculature." (PMID 26161255, 2015). "DLL4-induced Notch signaling, one of the mechanisms reported to mediate tumor resistance related to anti-VEGF therapy, activates multiple parallel pathways and induces the formation of large distorted vessels." (PMID 26394830, 2015). "Previous studies have shown that although Dll4/Notch blockade potentiates the tumor-driven angiogenic response, it inhibits tumor growth due to the formation of immature and poorly functional vessels that result in reduced tumor perfusion." (PMID 26314892, 2015). "Angiogenesis induced by DLL4-NOTCH1 signaling generates large vessels that increase tumor blood supply and diminish sensitivity to bevacizumab." (PMID 26394830, 2015). "Overexpression of Dll4 reduces neo-angiogenesis, but also differentiates vessels and downregulates VEGFR2 causing tumour resistance to anti-VEGF therapies." (PMID 25557927, 2015). "The present study was undertaken to assess the effects of targeted Dll4 allelic deletion in the incipient stages of tumor pathogenesis." (PMID 26314892, 2015). "Despite the wealth of information regarding the effects of Dll4/Notch inhibition in invasive neoplasms, little is known regarding its role in benign and early, pre-cancerous lesions." (PMID 26314892, 2015). "Tumor promoting effect of low-dosage inhibition needs to be considered when implementing Dll4 targeting therapies." (PMID 26314892, 2015). "In conclusion, the results show that the presence of high Dll4 expression levels was clearly associated with high VEGFR-2 expression levels, tumor grade, tumor stage and poor prognosis in CCRCC patients." (PMID 25364440, 2014). "Our study highlights the angiogenic mechanism by which blockade of Dll4 results in inhibition of tumor growth and vessel functionality." (PMID 25393540, 2014). "Given its specificity in the regulation of angiogenesis, the endothelial Dll4-mediated Notch signaling has been used as target for intervention in induction of new arteries or inhibition of tumor angiogenesis." (PMID 24689035, 2014). "Blockage of DLL4 signaling inhibits tumor growth by deregulating angiogenesis and promoting non–productive angiogenesis." (PMID 24931473, 2014). "Single agent inhibition of Dll4 signaling with REGN1035 induced a modest increase of Ki67 expression in RP-R-01 tumor sections, presumably reflecting increased endothelial proliferation." (PMID 25393540, 2014). "We found that treatment with the anti-mouse Dll4 monoclonal antibody REGN1035 produces potent single agent anti-tumor efficacy in these models." (PMID 25393540, 2014). "Sustained Wnt/β-catenin signaling increases Dll4 in tumor vessels and induces Notch signaling that mediates a reduced angiogenic response and normalizes tumor vasculature." (PMID 24689035, 2014). "In multivariate analysis, TNM stage, grade, tumor size, age and gender were analyzed, as well as expression levels of Dll4, using the Cox regression model." (PMID 25364440, 2014). "A few investigations focused on the effect of DLL4 in tumor progression via cell–cell communication." (PMID 24931473, 2014). "The same tumor model was applied to identify Dll4 as a mediator of tumor resistance to anti-VEGF therapy." (PMID 25601901, 2014).
tumor (continued). "Herein, we analyzed the anti-tumor activity of blocking Dll4-Notch signaling alone and in combination with anti-VEGF agents in patient-derived ccRCC models." (PMID 25393540, 2014). "Tumour response to Dll4 mAb, ultrasound-microbubbles and radiation combination therapy was also assessed with measurements of immunohistochemistry and tumour growth assays." (PMID 24736631, 2014). "We conducted experiments to assess the efficacy of vascular targeting strategies where USMB, radiation and anti-Dll4 treatments were combined to disrupt tumour vasculature and sustain vascular effects in order to maximize overall tumour response." (PMID 24736631, 2014). "Results presented in this study also confirm the importance of Dll4 in regulating ongoing tumour angiogenesis and its potential use in combination with other novel cancer therapies." (PMID 24736631, 2014). "Multiple tumor types have been found to express Dll4 and RCC, in particular, has been shown to be regulated by the Dll4/Notch pathway." (PMID 25393540, 2014). "The Notch ligand Delta-like 4 (Dll4) is highly expressed in vascular endothelium and has been shown to play a pivotal role in regulating tumor angiogenesis." (PMID 25393540, 2014). "In contrast, an increase of ∼ 25% in the VI for XRT+Dll4 mAb treated animals indicates a potential reperfusion of the tumour." (PMID 24736631, 2014). "VEGF was an important upstream factor of DLL4 during tumor developing angiogenesis and metastasis, and the anti-angiogenesis therapies for metastatic RCC majorly targeted VEGF." (PMID 24931473, 2014). "A recent study observed synergistic enhancement of tumour growth delay when a neutralizing Dll4 monoclonal antibody (mAb) was combined with radiation therapy." (PMID 24736631, 2014). "Treatment with Dll4 mAb then deregulates neo-vascularization, leading to minimally functional tumour vasculature and a sustained tumour vascular ‘collapse’." (PMID 24736631, 2014). "Species-specific Taqman RNA gene expression analysis was performed to determine the levels of Dll4 expression in the RP-R-01 model and to gain a better understanding of the anti-tumor mechanism of anti-Dll4 therapy." (PMID 25393540, 2014). "During tumor angiogenesis, DLL4 expression stimulated by VEGF is largely restricted to the tip cells of developing arteries, where it regulates the number of tip cells to control vessel sprouting and branching triggered by VEGF." (PMID 24931473, 2014). "The Notch ligand Delta-like 4 (DLL4) plays an important role in tumor angiogenesis, which is required for tumor invasion and metastasis." (PMID 24931473, 2014). "In conclusion, we report here the potent anti-tumor activity for the blockade of Dll4 as monotherapy and a benefit for the combined treatment of anti-Dll4 with VEGF pathway targeting agents in ccRCC PDX models." (PMID 25393540, 2014). "In our experimental setting, we did not observe single agent anti-tumor activity for the selective targeting of human, tumor cell-expressed Dll4 or anti-tumor additivity for the concomitant blocking of human (tumor cells) and murine (endothelial cells) Dll4." (PMID 25393540, 2014). "In our experimental models, we observed considerable single agent activity of Dll4 antibody targeting stromal Dll4, and an enhancement of the anti-tumor effects by combination with VEGF inhibition." (PMID 25393540, 2014). "In the current study, we showed that miR-30a directly targeted DLL4 and decreased tumor MVD, which suppressed ccRCC hematogenous metastasis." (PMID 23826258, 2013). "Recent studies have demonstrated that DLL4 expression can be found not only in peritumoral tissues, but also in the tumor cell itself." (PMID 23898884, 2013). "DLL4 was up-regulated in ccRCC and further increased in hematogenous metastatic cases, while miR-30a was down-regulated in tumor tissues and further decreased in hematogenous metastatic ccRCC (student t test, all p<0.05)." (PMID 23826258, 2013).
tumor (continued). "The endothelium-specific Notch ligand DLL4 is well documented to play important roles in embryonic vascular development and tumor angiogenesis." (PMID 23826258, 2013). "In particular, it has been elucidated that the Notch Delta-like ligand 4 (DLL4) regulates tumor angiogenesis, and plays key roles in tumor neovascularity." (PMID 23898884, 2013). "Compared with non-tumor tissues, miR-30a expression, detected by real-time PCR, decreased about 10 fold in ccRCC, whereas DLL4 expression was elevated approximate 20 fold (student t test, both p<0.05)." (PMID 23826258, 2013). "By univariate analysis, tumor depth, nodal involvement, lymphatic invasion, and DLL4 positivity were found to be significant prognostic markers." (PMID 23898884, 2013). "Its implication in angiogenesis has been particularly under investigation in cancer research, notably by the development of Dll4 antibodies or γ-secretase inhibitors to reduce tumor growth." (PMID 23531541, 2013). "The Notch ligand delta-like 4 (Dll4) has recently emerged as a critical regulator of tumor angiogenesis." (PMID 23967403, 2013). "Both cancer and stromal DLL4 expression significantly correlated with more advanced tumor depth, nodal involvement, and lymphatic and venous invasion." (PMID 23898884, 2013). "Endothelial DLL4 plays an important role in controlling of tumor angiogenesis, which is required for tumor invasive growth and metastasis." (PMID 23826258, 2013). "Dll4 inhibition, and sDll4-Fc therapy in particular, have shown potential in controlling tumor growth, even in cases when tumors have gained resistance to anti-VEGF therapies." (PMID 22279550, 2012). "This important function has led to the development of therapies blocking Dll4 function for tumor therapy." (PMID 22279550, 2012). "Dll4 targeting increased tumor vascular sprouting and branching, but with poor perfusion and therefor suppressed tumor growth." (PMID 24213317, 2012). "In particular, DLL4 is required for vascular development and is strongly expressed in tumor vessels." (PMID 23028940, 2012). "SIRT1 inhibits the acetylated form of N1IC and significantly diminishes N1IC activity induced by p300, thereby limiting the DLL4/Notch signaling response and inhibiting tumor angiogenesis." (PMID 23028940, 2012). "Blocking Dll4 signaling by administration of Dll4-Fc protein gave rise to increased vascular density but reduced tumor growth." (PMID 24213317, 2012). "Disruption of DLL4 signaling in combination with anti-VEGF treatment has shown additive effects on tumor growth." (PMID 22007214, 2012). "The first trials of anti-Dll4 therapy in mice demonstrated a paradoxical effect, as it reduced tumor perfusion and growth despite leading to an increase in vascular density." (PMID 22279550, 2012). "DLL4 expression on ECs activates the Notch signaling pathway, which results in the regulation of tumor angiogenesis in a VEGF-independent manner." (PMID 22007214, 2012). "The work on DLL4 shows that up-regulation of VEGF in tumor vasculature can also have a therapeutic benefit." (PMID 21831306, 2011). "In particular, the Notch ligand Dll4 (delta-like 4) has been identified as a promising new target in tumor angiogenesis in preclinical studies." (PMID 21923938, 2011). "In various mouse models, strong Dll4 expression was observed in the majority of tumor vessels, contrasting with significantly lower vascular expression in adjacent normal tissues." (PMID 21923938, 2011). "Studies utilizing a DLL4-selective antagonistic antibody demonstrate that DLL4 is also essential for early postnatal vascular development, angiogenesis during pathological wound healing (unpublished observations) and tumor angiogenesis." (PMID 21824400, 2011). "It has been shown that DLL4 inhibition can have a widespread effect in reducing tumor growth in a number of different xenograft models through this angiogenic mechanism." (PMID 21831306, 2011).
tumor (continued). "Vessel instability has been previously observed in other studies looking at the importance of Dll4 during tumor angiogenesis and also embryonic vasculogenesis, but this effect was not related to the contribution/involvement of BM-VPC." (PMID 21483741, 2011). "Recently generated Notch1-specific inhibitory antibodies exhibited tumor vessel effects similar to those seen following blockade to Dll4." (PMID 21923938, 2011). "The endothelial Notch ligand Dll4 (delta-like 4) has recently emerged as a critical regulator of tumor angiogenesis and thus as a promising new therapeutic anti-angiogenesis target." (PMID 21923938, 2011). "From a therapeutic standpoint, it will be instrumental to identify the tumor types that will benefit most from ani-Dll4 therapy and to further validate combination approaches with anti-angiogenic and chemotherapeutic regimens." (PMID 21923938, 2011). "The endothelial cell Notch ligand Dll4 has recently emerged as a critical regulator and a promising target in tumor angiogenesis." (PMID 21923938, 2011). "Evidence of increased Dll4 expression in the tumor endothelium correlates with tumor vessel maturation and remodeling." (PMID 22087289, 2011). "Although blockade of Dll4 results in an abnormalization of the tumor vasculature, combining Dll4 inhibition with cytotoxic chemotherapy frequently results in enhanced anti-tumor activity in preclinical tumor models (; Kirshner and Thurston, unpublished)." (PMID 21923938, 2011). "In vivo, transplantation of BM-VPC with decreased Dll4 into tumor-bearing mice resulted in the formation of microvessels with decreased pericyte coverage and reduced fibronectin expression." (PMID 21483741, 2011). "More work is needed to understand the factors that regulate Dll4 expression in tumors and to extend the connection between Dll4 expression and tumor progression." (PMID 21923938, 2011). "This review aims to provide current perspectives on the function of Dll4-Notch signaling axis during tumor angiogenesis and on mechanisms and applications of targeting this pathway for cancer therapy." (PMID 21923938, 2011). "Inhibition of DLL4 signaling has been shown to result endothelial cell hyperproliferation and increased vascular sprouting in tumor angiogenesis." (PMID 21831306, 2011). "DLL4 inhibition by shRNA or by the DLL4 neutralizing antibody YW152F significantly reduced the number of BM-derived pericytes/vSMC within the tumor, reduced vessel functionality (indicated by increased hypoxia), and inhibited tumor growth in vivo." (PMID 21785569, 2011). "Soluble DLL4 was also able to reduce the recruitment of pericytes in a murine xenograft tumor model." (PMID 21824400, 2011). "Preclinical studies have highlighted that both anti-CSC and anti-angiogenic activities contribute to its anti-tumor efficacy, and have supported the clinical development of anti-DLL4 antibody for the treatment of cancer." (PMID 21831306, 2011). "Taken together, these data show the tumor vessels grown in BM Dll4+/− BM-VPC transplanted versus control mice or those with BM-VPC-WT are non-functional, leaky vessels." (PMID 21483741, 2011). "Robust Dll4 expression was observed specifically in the tumor vasculature in all of these tumor types, whereas Dll4 expression was low to undetectable in the vasculature of adjacent normal tissue." (PMID 21923938, 2011). "Agents targeting VEGF, the major chemotactic stimulus for recruiting BM cells to the tumor, and DLL4, an important molecular signal for the differentiation of BM-derived cells into pericytes/vSMCs, are currently being evaluated for clinical efficacy." (PMID 21785569, 2011). "Pharmacological targeting of Dll4-Notch signaling in preclinical tumor models has been achieved by several different mechanisms including anti-Dll4 antibodies, DNA vaccination, soluble Dll4-Fc and Notch-Fc decoys, Notch antibodies, and γ-secretase inhibitors." (PMID 21923938, 2011).
tumor (continued). "Results from a flurry of recent studies confirmed that targeting DLL4/NOTCH1 signaling has a profound impact on tumor angiogenesis and growth." (PMID 21824400, 2011). "Across a range of major tumor types, including colorectal, kidney, breast and lung cancer, DLL4 protein expressed by tumor cells can be detected in a high percentage of patient samples." (PMID 21831306, 2011). "Anti-DLL4 treatment was shown to have synergistic activity with various chemotherapeutic agents in reducing tumor volume and tumor initiating cell frequency." (PMID 21831306, 2011). "Globally, the results presented here show that gene expression alterations in the ligand Dll4 on BM-VPC regulate angiogenesis at the tumor site." (PMID 21483741, 2011). "Blockade of Dll4-Notch resulted in tumor growth inhibition in a variety of human and rodent tumor models associated with the formation of a non-functional, hypersprouting tumor vasculature." (PMID 21923938, 2011). "The differential expression between tumor and normal vessels likely explains the preferential targeting of Dll4-expressing tumor endothelial cells in preclinical tumor models." (PMID 21923938, 2011). "Recent studies revealed that the Notch signalling pathway, and specifically its ligand Dll4, is crucial for adequate tumor angiogenesis." (PMID 21483741, 2011). "Dll4 expression on EC activates the Notch signalling pathway resulting in the regulation of tumor angiogenesis in a VEGF-independent manner." (PMID 21483741, 2011). "We then used Western blotting to estimate levels of Dll4, a Notch ligand known to be upregulated during tumor angiogenesis, and EphrinB2, a downstream target of Dll4." (PMID 22087289, 2011). "Paralleling vascular development, Dll4 expression in tumor vessels appears to be directly regulated by VEGF; thus Dll4 expression levels in tumors have been found to correlate with those of VEGF." (PMID 21923938, 2011). "Combination treatment of irinotecan with anti-hDLL4 reduced again the tumor growth and stem cell frequency, at even higher levels than the anti-DLL4 treatment alone." (PMID 21311095, 2010). "We studied the effects of Dll4 allelic deletion and of systemic administration of sDll4 on the tumor vasculature." (PMID 21092311, 2010). "The reduction of the average tumor volume was even more pronounced in sEphB4-Alb treated RT2 Dll4+/- group (approximately 90% reduction, p < 0.01) where Dll4/Notch and Ephrin-B2/EphB4 signaling were simultaneously inhibited." (PMID 21092311, 2010). "We sought to determine the effect of combined blockade of Dll4/Notch pathway (by sDll4) and Ephrin-B2/EphB4 pathway (by sEphB4-Alb) on tumor angiogenesis." (PMID 21092311, 2010). "By inhibiting DLL4 with human monoclonal antibody 21M18 in colon carcinoma xenografts, the tumor growth as well as the CSC frequency, measured by the amount of ESA+CD44+CD166+ cells is decreased compared to control." (PMID 21311095, 2010). "Dll4/Notch and Ephrin-B2/EphB4 pathways play critical roles in tumor vessel development and maturation." (PMID 21092311, 2010). "In summary, targeting of Dll4/Notch and Ephrin-B2/EphB4 in combination showed marked improvement in tumor growth inhibition." (PMID 21092311, 2010). "The lack of overlapping effects is consistent with the fact that Dll4 targeted therapy has a markedly increased number of tumor vessels while sEphB4-Alb therapy results in significantly reduced tumor vessel density." (PMID 21092311, 2010). "Dll4 is critical for embryonic vascular development and arterial specification and is markedly induced in murine and human tumor vessels." (PMID 21092311, 2010). "Although forced expression of Dll4 in tumor cells results in decreased tumor vessel branching and increased vessel diameter, it promotes tumor growth rather than cell death." (PMID 20691046, 2010).